TP53BP2 (tumor protein p53 binding protein 2)
Description:
Inhibits the ability of NAE1 to conjugate NEDD8 to CUL1, and thereby decreases NAE1 ability to induce apoptosis. Impedes cell cycle progression at G2/M. Its apoptosis-stimulating activity is inhibited by its interaction with DDX42.
Synonyms: Bbp; 53BP2; p53BP2; ASPP2; PPP1R13A
Tractability: Small molecule: a structure with a bound ligand is known. PROTAC: ubiquitination databases record sites on it.
Gene: Protein-coding gene on chromosome 1 (223,779,893 to 223,845,954, reverse strand). Ensembl gene ENSG00000143514.
Subcellular location: Cytoplasm, perinuclear region; Nucleus
Subcellular location (Human Protein Atlas): Cell Junctions; Cytosol
Pathways (Reactome):
Programmed Cell Death: Activation of PUMA and translocation to mitochondria
Gene Ontology:
Molecular function: identical protein binding; NF-kappaB binding; protein binding; protein homodimerization activity
Biological process: positive regulation of execution phase of apoptosis; negative regulation of cell cycle; signal transduction; regulation of apoptotic process
Cellular component: cell junction; cytoplasm; cytosol; nucleus; perinuclear region of cytoplasm; nucleoplasm
Genetic constraint (gnomAD): Loss-of-function variants: 57 observed, 122.42 expected, observed/expected ratio (o/e) 0.47, 90% interval 0.38 to 0.58. The upper end of that interval is the gene's LOEUF score, 0.58, which puts it in group 2 of 6, group 1 being the genes least tolerant of losing a copy. Missense variants: 1,179 observed, 1,432.5 expected, observed/expected ratio (o/e) 0.82, 90% interval 0.78 to 0.86. Synonymous variants: 479 observed, 520.9 expected, observed/expected ratio (o/e) 0.92, 90% interval 0.85 to 0.99.
Gene-disease validity (ClinGen):
ClinGen rates the evidence that TP53BP2 causes each of these diseases.
open-angle glaucoma (autosomal dominant): Disputed. Chronic outflow obstruction of the eye's drainage canals that can lead to increased internal eye pressure and optic nerve damage.
Homologues: Orthologues: chimpanzee TP53BP2 (99% identical), macaque TP53BP2 (99% identical), mouse Trp53bp2 (91% identical), pig TP53BP2 (91% identical), rabbit TP53BP2 (90% identical), dog TP53BP2 (89% identical), rat Tp53bp2 (88% identical), guinea pig TP53BP2 (82% identical), tropical clawed frog tp53bp2 (69% identical), zebrafish tp53bp2a (59% identical), zebrafish tp53bp2b (58% identical), Drosophila melanogaster ASPP (26% identical), and 1 more. Paralogues in human: PPP1R13B (47% identical).
Diseases named in the same sentence as TP53BP2 in open-access papers:
TP53BP2 is named in the same sentence as 75 diseases in open-access papers, as found by Europe PMC text mining. Sharing a sentence is not in itself a finding about the gene and the disease. The quoted sentences say what the papers report.
breast carcinoma (26 papers, 2007 to 2025). "TP53BP2 (ASPP2) inhibition accelerates cell migration, invasion, and epithelial-mesenchymal transition in breast cancer cells." (PMID 34635181, 2021). "This lends credence to the idea that genetic variation at this locus influences breast cancer survival through regulation of one or both of the genes TP53BP2 and FBXO28." (PMID 28179588, 2017). "Whereas the overexpression of TP53BP2 promoted the proliferation and induced less apoptosis of breast cancer cells." (PMID 26663100, 2016). "Alter expression of TP53BP2 in human tumours has been shown in a number of cancer types, including down-regulation in breast cancer and lung cancer." (PMID 25969993, 2015). "TP53BP2 mRNA expression is frequently downregulated in human breast cancer." (PMID 29504908, 2018). "Overexpression of TP53BP2 promoted the proliferation in breast cancer cells." (PMID 28423713, 2017). "Our study showed that miR‐548d‐3p/TP53BP2 pathway is critically involved in the proliferation and apoptosis of breast cancer cells and may be new therapeutic target of breast cancer cells." (PMID 26663100, 2016). "The miR‐548d‐3p/TP53BP2 pathway axis is critically involved in the breast cancer genesis." (PMID 26663100, 2016). "At the TP53BP2 gene promoter in HeLa cells and the RASSF1A gene promoter in MDAMB-231 breast cancer cells, SETDB1 interacts preferentially with the de novo DNA methyltransferase DNMT3A, but not with the maintenance methyltransferase DNMT1." (PMID 38904842, 2024). "Reduced expression of TP53BP2 has been linked with poor distant recurrence-free surival in breast cancer patients and was observed in metastatic breast cancer samples compared to non-metastatic samples, suggesting that TP53BP2 may be associated with breast cancer progression." (PMID 25969993, 2015). "At the TP53BP2 gene promoter in HeLa cells and the RASSF1A gene promoter in MDAMB-231 breast cancer cells, SETDB1 interacts with DNMT3A, but not with the maintenance methyltransferase DNMT1." (PMID 38904842, 2024).
gastric cancer (9 papers, 2007 to 2025). A primary or metastatic malignant neoplasm involving the stomach. "Four single nucleotide polymorphisms in TP53BP2 are significantly correlated with gastric cancer susceptibility." (PMID 29504908, 2018). "Four single nucleotide polymorphisms (g.206692C>T, g.198267A>T, g.164895G>A and g.152389A>T) within TP53BP2 showed a significant link with gastric cancer susceptibility." (PMID 17211478, 2007). "Furthermore, an association between the ASPP2 (TP53BP2) locus and gastric cancer susceptibility has also been reported." (PMID 17211478, 2007).
liver cancer (6 papers, 2016 to 2022). An epithelial or non-epithelial malignant neoplasm that arises from the liver. "CAP2 was coexpressed with TP53BP2, ENA/VASP in the liver cancer, and CFL1, CFL2, DSTN, ACTB, ACTG1, and ROBO1." (PMID 28423713, 2017). "CAP2 was coexpressed with TP53BP2 and ENA/VASP in liver cancer." (PMID 28423713, 2017).
breast tumours (5 papers, 2007 to 2017). "While TP53BP2 was not a predicted target in our computational analysis, variants in strong LD with rs10916264 did associate with its expression in breast tumors." (PMID 28179588, 2017).
melanoma (3 papers, 2013 to 2021). A malignant, usually aggressive tumor composed of atypical, neoplastic melanocytes. "Supporting this hypothesis, a slight up-regulation of the TP53BP2 gene has been reported in our melanoma model (FC = 2.36)." (PMID 23642048, 2013).
squamous cell carcinoma (3 papers, 2016 to 2017). A carcinoma arising from squamous epithelial cells. "TP53BP2 can bind IκB and induce repression of p63 through NF-κB, suppressing tumorigenesis and metastasis in squamous cell carcinoma." (PMID 28179588, 2017).
glioma (2 papers, 2016 to 2023). A benign or malignant brain and spinal cord tumor that arises from glial cells (astrocytes, oligodendrocytes, ependymal cells). "The oncogenic effect of miRNA-21 in human glioma cells is implemented through the suppression of such tumor suppressor genes as TAp63, HNRPK, JMY, TOPORS, RECK, TP53BP2, TIMP3, PDCD4, and TGFBR2/3." (PMID 37033545, 2023).
COVID-19 (1 paper, 2024). A disease caused by infection with severe acute respiratory syndrome coronavirus 2. "In the COVID-19 comparison group, five DEPs, PPP1CA, YWHAH, YWHAB, YWHAZ, and TP53BP2, were enriched with the first three upregulated and TP53BP2 downregulated, whereas the PQ group exhibited enrichment only in Smad4 within this pathway." (PMID 39301288, 2024).
glaucoma (1 paper, 2018). Increased pressure in the eyeball due to obstruction of the outflow of aqueous humor. "Taken together, these studies support the involvement of the TP53BP2 gene in glaucoma and suggest that the genetic variant identified by WES in the large POAG family may be relevant to the disease." (PMID 28150229, 2018). "Since it has been demonstrated that the gene regulates apoptosis in RGCs and is downregulated upon minocycline treatment in a glaucoma rat model, TP53BP2 may represent a novel gene associated with POAG." (PMID 28150229, 2018). "In another recent study, the neuroprotective effect of minocycline in rats with glaucoma was evaluated, and downregulation of TP53BP2 was observed upon treatment." (PMID 28150229, 2018).
tumor (57 papers, 2007 to 2026). "TP53BP2 is a key regulator of epithelial plasticity that connects cell polarity to suppress tumor metastasis." (PMID 26663100, 2016). "In contrast to the MDM2-EP300 example, the most advantageous outcome for the tumor would seem to result if mutations at residues 181, 247 and 249 compromised both TP53BP1 and TP53BP2 interactions." (PMID 27043210, 2016).
cancer (48 papers, 2007 to 2025). A tumor composed of atypical neoplastic, often pleomorphic cells that invade other tissues. "TP53BP2 has been reported to be associated with many kinds of cancers." (PMID 26663100, 2016). "For example, TP53BP2, CDK11A, MME and SEPT6 are mutated in MCF10CA1a cells and have strong correlations to a number of cancers." (PMID 25969993, 2015).
TP53BP2 also shares sentences with these, for which no sentence is quoted: hepatocellular carcinoma (16 papers); colorectal cancer (10); lung carcinoma (8); pancreatic cancer (6); infection (5); leukemia (5); lymphoma (5); acute leukemia (4); diffuse large B-cell lymphoma (3); gallbladder cancer (3); non-alcoholic fatty liver disease (3); steatosis (3); Alzheimer disease (2); choriocarcinoma (2); colon cancer (2); esophageal cancer (2); Hepatic steatosis (2); liver failure (2); pituitary adenoma (2); proliferative vitreoretinopathy (2); sarcoma (2); triple-negative breast carcinoma (2); Acute hepatitis (1); adenoma (1); anorexia nervosa (1); bladder cancer (1); cervical cancer (1); chronic hepatitis B (1); Cirrhosis (1); co-infection (1).
A further 34 diseases each share a sentence with TP53BP2 in 1 paper.